IL17A (interleukin 17A)
Diseases named in the same sentence as IL17A in open-access papers (continued):
Sharing a sentence is not in itself a finding about the gene and the disease.
Autoimmunity (continued). "IL-17A induces early immune responses against infections, participates in autoimmunity and is responsible for destructive inflammatory conditions." (PMID 35586340, 2022). "It has been found to modulate Th17 autoimmunity through transcriptional suppression of the pro-inflammatory cytokine IL-17, via recruitment of histone deacetylase 2 to the IL17A promoter region." (PMID 36296970, 2022). "Specifically, the emerging interest in autoimmunity in systemic sclerosis (Scleroderma, SSc) has led to potential role of IL-17A as a target therapy in this disease." (PMID 35603223, 2022). "IL-17A and IL-17F are eponymous cytokines of the Th17 cell lineage, and IL-17A is believed to have a greater influence on driving autoimmunity than IL-17F because of its more potent signaling ability." (PMID 36569854, 2022). "Biological features of the two cytokines appear to be distinct, with IL-17F being best characterized as a mediator of mucosal immunity and IL-17A as an important mediator of inflammatory reactions and autoimmunity." (PMID 36366333, 2022). "Nevertheless, in regard to autoimmunity and chronic inflammatory diseases, IL-17A, IL-17C and IL-17F act as the key mediators in manipulating the pathway cellular machinery." (PMID 35203707, 2022). "In the context of several mouse experimental models of both infection and autoimmunity, the expression of IL-17A has been connected to the migration of neutrophils." (PMID 36139450, 2022). "When compared with heterozygous keratinocyte cell lines, PCSK9 SNP rs662145 C > T homozygous cell lines expressed low levels of PCSK9 and high levels of IL36 cytokines, a family of cytokines induced by IL-17A in autoimmunity and inflammatory skin conditions." (PMID 35862195, 2022). "Th17 cells, characterized by the secretion of IL-17A (also called IL-17), IL-17F, IL-22 and other cytokines, can induce autoimmunity by promoting tissue inflammation and mobilizing innate immunity." (PMID 36235230, 2022). "Targeting the RORγt/IL-17A/IL-23 axis, either by genetic manipulation or antibody-mediated neutralization of pathway cytokines (e.g. IL-17A, IL-23 and GM-CSF) ameliorates disease pathology in multiple animal models of autoimmunity and inflammation." (PMID 34752458, 2021). "Taken account that IL-17a is a key factor contributing to endothelial dysfunction in this TLR7-driven lupus autoimmunity model, we next examined the changes brought by the antibiotics on the observed SLE-linked endothelial dysfunction." (PMID 34573058, 2021). "IL-17 comprises a family of cytokines IL-17A to IL-17F in that IL-17A is the most abundant one against microbial infections and is involved in inflammation and autoimmunity." (PMID 34943909, 2021). "In models of autoimmunity including inflammatory bowel disease or nephritis, IL-10 effects largely depend on the inhibition of IL-17A pathways." (PMID 34772416, 2021). "The negative correlation between the proportion of ILC2s with IL-6 and IL-17A further confirmed the negative regulatory role of ILC2s in inflammation and autoimmunity." (PMID 33688303, 2021). "During post stroke inflammation, IL-10 seems to directly inhibit the IL-17A production in Th17 cells in ischemic brains, which is a known mechanism from other models of autoimmunity." (PMID 34772416, 2021). "As the subpopulation of T helper cells, Th17 cells produce IL-17 A/IL-17F and play a pivotal role in inflammation, autoimmunity, and host defense against extracellular pathogens." (PMID 34194525, 2021). "Th17 cells and their characteristic IL-17A cytokine are considered the initiators of various autoimmune conditions." (PMID 34446083, 2021). "Treatment with OA also reduced the indices of inflammation and autoimmunity in colon tissues, (i.e., increased TNFα, IL-1β, IL-23, IL-17A, and KC; and reduced IL-13, IL-33, and IL-25)." (PMID 33246492, 2020).
Autoimmunity (continued). "Therapeutic targeting of IL-17A and its receptor IL-17RA with antibodies has turned out to be a tremendous success in the treatment of several autoimmune conditions." (PMID 32174926, 2020). "Although HES treatment in our study did not offer long-term protection from EAE, a significant reduction in pMOG-specific IL-17A indicated that some aspects of autoimmunity are suppressed, although overall disease symptoms eventually appear regardless." (PMID 33117327, 2020). "An early study indicated that IL-25 exerts an opposite function in the pathogenesis of organ-specific autoimmunity compared to IL-17A." (PMID 33132897, 2020). "IL-17RA-RE is also expressed on activated Th17 cells, and when triggered by IL-17C, it favors IL-17A, IL-17F, and IL-22 production by mouse Th17 cells, potentiating the adaptive immune response against pathogens and in autoimmunity." (PMID 33244315, 2020). "This is in keeping with other studies demonstrating overlapping functions of IL-17F and IL-17A in models of autoimmunity and pathogen clearance." (PMID 32753746, 2020). "Today, six IL-17 homologous molecules are known (IL-17A-F) and most of the research is focusing on IL-17A and IL-17F which were shown to be important for autoimmunity and inflammation." (PMID 29931394, 2018). "Numerous studies have demonstrated the involvement of T-helper 17 (Th17) cells, the primary producers of IL-17A, in autoimmunity." (PMID 29995930, 2018). "IL-17A knockout (KO) or IL-17A blockade abolishes disease development in animal autoimmune models such as experimental autoimmune encephalomyelitis (EAE) and collagen-induced arthritis (CIA)." (PMID 30214937, 2018). "IL-17A is a potent amplifier of ongoing inflammation, which plays an important role in the progression of chronic inflammation and autoimmunity." (PMID 28188344, 2017). "Th17 cells are an identified subset of effector CD4+ T cells, and IL-17A, the major cytokine released from these or other IL-17-producing cells, have been discovered to mediate autoimmunity and immune defense against pathogens." (PMID 28039485, 2017). "Due to its lower affinity, IL-17F seems to be less proinflammatory and IL-17A is more critical than IL-17F in mediating inflammation and autoimmunity, such as in experimental autoimmune encephalomyelitis (EAE)." (PMID 28210632, 2017). "IL-17A has been widely studied in autoimmunity and is thought to play a pivotal role in SLE physiopathology." (PMID 29178890, 2017). "Among the members of this family, IL-17A or IL-17, and IL-17F are mostly studied due to their important functions in immune response and autoimmunity." (PMID 27308096, 2016). "Many studies have investigated the role of IL-17A, often referred to as IL-17, in inflammation, autoimmune disorders and tumors." (PMID 26812681, 2016). "Here, we show the guanine nucleotide exchange factor, Tiam1, and its cognate Rho-family G protein, Rac1, regulate interleukin (IL)17A transcription and autoimmunity." (PMID 27725632, 2016). "IL-17A has also been noted to increase in mice and humans with aging and to participate in autoimmunity." (PMID 27623073, 2016). "IL-17A is the most characterized of the IL-17 family of cytokines (IL-17A through IL-17 F) that also play roles in inflammation, T cell responses and autoimmunity as previously reviewed." (PMID 25849622, 2015). "MPO-ANCA triggers the production of IL-6, IL-17A and IL-23 and increases the activation of neutrophils, conditions that promote Th17-mediated autoimmunity." (PMID 25964886, 2015). "GM-CSF and IL-22 are both emerging as key players in autoimmunity, sometimes more potent than IL-17A in the development of disease." (PMID 25148371, 2014). "In summary, although it is generally considered that IL-17A neutralization prevents inflammation and autoimmunity, we demonstrated a protective role of this cytokine by Th1-Th17 reciprocal regulation." (PMID 24146810, 2013).
Autoimmunity (continued). "Th17 T cells: CD4+ T cells and γδ T cells that express T-helper 17 (Th17)-type cytokines, such as IL-17A, and mediate immune responses against bacterial and fungal infections, as well as autoimmunity." (PMID 23828644, 2013). "The key cytokine responsible for the proinflammatory autoimmunity in these models appear to be IL-17A and IFN-γ is known to inhibit Th17 polarization." (PMID 23577183, 2013). "The unique cytokine of Th17 is IL-17 which has several isoforms of which IL-17A and IL-17F appear to be important in regulating immune responses in autoimmunity." (PMID 23936569, 2013). "In the IL-17 cytokine family, IL-17A was identified as the main cytokine involved in the pathogenesis of autoimmunity, inflammation, and host defense." (PMID 24376862, 2013). "An additional T-cell subset, distinct from IFN-γ-producing Th1 cells as well as Th2 cells, capable of inducing inflammation and autoimmunity, is named Th17 and produces IL-17A, -17F, -21 and IL-22." (PMID 24710420, 2012). "The importance of IFN-γ and IL-17A in autoimmunity has been established in both humans and animal models." (PMID 22969766, 2012). "IL17A and IL17F are mainly produced by a subset of CD4+ T cells (Th17 cells) and have been linked to a variety of inflammatory and autoimmune conditions." (PMID 22216338, 2011). "The differential role of IL-17A and IL-17F raises interesting questions in deciphering mucosal immunity and autoimmunity." (PMID 22164330, 2011). "Recently, CD4+IL-17A+ T helper 17 (Th17) cells were identified and reported in several diseased states, including autoimmunity, infection and various peripheral nervous system tumors." (PMID 21060663, 2010). "Similarly, in the experimental autoimmune encephalomyelitis (EAE) model of MS, TH17 cells act as potent inducers of autoimmunity, with IL-17A-/- mice exhibiting significantly attenuated disease." (PMID 41248187, 2025). "Thus, the IL-17a cytokine family plays a dual role in immunity, being indispensable for host defense while also contributing to chronic inflammation and autoimmunity." (PMID 41310729, 2025). "Finally, both strains showed an upregulation of IL-17 A/F, related to a Th17 response, important in autoimmunity." (PMID 38409078, 2024). "Another IL-17A blocker is ixekizumab, which is also widely used in various autoimmune conditions." (PMID 39201060, 2024). "It is reported that IL-17A activation of the receptor is 10 to 30 times more potent than IL-17F binding, which emphasizes the differences in affinity and the vital role that IL-17A plays in driving autoimmunity." (PMID 39493750, 2024). "As revealed by evidencing studies, NLRC3 increases many genes related to the activation of Th1/Th17/T cells, such as Ifng, Tnf, Il17f, Il17a, and Tbx21; also, study reveals that Nlrc3 expression in T cells inhibits autoimmunity as well as CD4+ T cell responses specific for virus." (PMID 38436712, 2024). "Both CD4+ and CD8+ T cells produce IL-17A and play important roles in autoimmunity." (PMID 36817487, 2023). "Generally, responses to IL-17A signalling are stronger than those to IL-17F, which may account for the predominant role of IL-17A in promoting autoimmunity." (PMID 37373452, 2023). "Rac1 is necessary for IL-17A expression and induction of autoimmunity in mice." (PMID 37834058, 2023). "Dysregulated IL-17A and IL-17F contribute to chronic inflammation and autoimmunity." (PMID 37834058, 2023). "It is now well established that IL-17A is involved in autoimmunity and in chronic inflammation." (PMID 35479069, 2022). "Therein, IL17A/F modulate intestinal homeostasis and facilitate autoimmunity in the CNS." (PMID 35747061, 2022). "IL-17A has pleiotropic effects with a key role in host defense against extracellular pathogens, including bacteria and fungi, but also in chronic inflammation and autoimmunity." (PMID 35479069, 2022).
Autoimmunity (continued). "The summary of observations provided by this review may have empowering implications for IL-17A-based strategies to prevent clinical manifestations in a broad spectrum of autoimmune conditions." (PMID 35620115, 2022). "Given the available data thus far, targeting IL-17A may be considered a novel strategy to prevent clinical manifestations in a broad spectrum of autoimmune conditions." (PMID 35620115, 2022). "Thus, our study provides a mechanism for Th17 cell-mediated dopaminergic cell death via secretion of inflammatory IL-17A, thereby implicating autoimmunity in LBD." (PMID 34648304, 2021). "Two emerging T helper (Th) cell subsets, Th17 and Th22 cells, and their respective prototype cytokines interleukin 17A (IL-17A) and IL-17F and IL-22, link the immune response to tissue inflammation, and play important roles in host defense, autoimmunity, and allergic diseases." (PMID 33718260, 2021). "Although mammalian IL-17A and IL-17F play important and similar roles in inflammation, IL-17A can induce inflammatory cytokines more strongly than IL-17F in the autoimmunity, and IL-17F plays a more critical role than IL-17A in protecting colonic epithelial cells from bacterial invasion." (PMID 34267744, 2021). "Furthermore, IL-17A induced inflammatory cytokines more strongly than IL-17F in the autoimmunity, but IL-17F has more critical roles than IL-17A in protecting colonic epithelial cells against the invasion of bacteria." (PMID 34267744, 2021). "IFN-γ is a well-known Th1 cell-produced cytokine, TNF-α is associated with a pro-inflammatory state and may also be secreted by Th1 cells, and IL-17A is a marker of CD4+ Th17 lymphocytes, which are associated with autoimmunity, inflammation, and chronic pain." (PMID 32497151, 2020). "IL-17A is mainly involved in a number of autoimmune disorders." (PMID 32823524, 2020). "In this regard, neutralizing antibodies against IL-17A and IL-17RA, which have been tested safe and effective for the treatment of autoimmunity in humans, may be tested as adjuvant therapies that accompany current cancer immunotherapies." (PMID 31775909, 2019). "Furthermore, we show that intestinal regulation of the gut microbiota by IL-17A modulates systemic autoimmunity suggesting a yin-yang relationship between the gut microbiota and Th17 cell responses." (PMID 30894857, 2019). "Therefore, RA indirectly diminishes the Th17 response that is a major contributor of autoimmunity, as IL-17A production from γδ T cells has been proposed to augment the Th17 response." (PMID 30081517, 2018). "In addition to the Th subsets, cytotoxic T cells expressing IFN-γ or IL-17A (Tc1 and Tc17 respectively) have been identified as propagating autoimmunity in other diseases." (PMID 28970488, 2017). "IL-6 is a known pro-inflammatory cytokine that in the presence of increased levels of TGF-β, as in hepatic fibrosis, promotes the differentiation of naiive T lymphocytes to Th17 cells, characterized by autoimmunity and secretion of a pro-inflammatory cytokine profile, including IL-17A." (PMID 29176797, 2017). "Interleukin-17A (IL-17A) is one of the main cytokines which is produced by Th17 lymphocytes and stimulate several inflammatory conditions against microbes and during immune system-related diseases including chronic inflammation diseases and autoimmunity." (PMID 26330848, 2015). "Increased levels of IL-17 F have also been detected in autoimmunity, suggesting that IL-17 F may play a similar role to that of IL-17A." (PMID 26021566, 2015). "Hence, agents that inhibit the Th17 pathway at multiple points, including inhibitors of JAK kinases, IL-23, IL-17A and IL-17RA, are currently being used or evaluated in RA and other autoimmune conditions." (PMID 24513269, 2014). "However, IL-17A plays important roles in the development of autoimmunity, inflammation and tumors and in host defense against bacterial and fungal infections, whereas IL-17F has a role mainly in mucosal host defense mechanisms." (PMID 24454477, 2013).
Autoimmunity (continued). "Indeed, Th17 cells, whose development in human is mainly induced in response to IL-23 and IL-1β, release interleukin-17A that exhibits potent proinflammatory properties in animal models of autoimmunity, including EAU." (PMID 24312163, 2013). "IL-17A also contributes to autoimmunity by triggering a positive feedback loop via IL-6 induction." (PMID 24454477, 2013). "IL-17A, which is produced mainly by Th1 and Th1/Th17 cells, mediates autoimmunity and immune defense against pathogens, and is increased in the intestinal mucosa of patients affected by chronic inflammatory bowel disorders, such as celiac disease, CD, and ulcerative colitis." (PMID 23834907, 2013). "Although the newest data implied that the IL-17A-producing Th17 lineage appeared to supplant Th1 cells in promoting autoimmunity, our data showed that the Th1 phenotype might also act as pathogenic agents in CIA." (PMID 21858123, 2011). "The pathogenesis of LVA secondary to viral myocarditis is unclear, which may be in connection with the long-term fiber scar repair of the necrotic myocardium, while Th17 cells/IL-17A-mediated autoimmunity and myocardial fibrosis may involve DCM formation post-myocarditis." (PMID 38836060, 2024). "Second, IL-17A may represent a driving force behind autoimmunity." (PMID 35620115, 2022). "In addition, similar to other models of autoimmunity, depletion of IL17A and, more importantly, IL17RC may reduce the severity of eye disease after HSV-1 infection by affecting both IL17A and IL17F functions." (PMID 32516406, 2020). "This may be related to the recent data indicates the involvement of EBV in inflammatory reactions via the modulation of two major cell compartments: Th17 cells which contribute to the development of inflammation and autoimmunity by producing IL-17A, and T reg cell activities." (PMID 33121089, 2020). "IL-17A and IL-17F are the most studied proteins of the IL-17 cytokine family, with both proteins pro-inflammatory under most of the conditions studied and may participate in driving autoimmunity." (PMID 30161145, 2018). "In addition, given the possible importance of IL-17A in autoimmunity, it is of interest to note the growing evidence that autoimmunity may contribute to the pathogenesis of COPD." (PMID 25427574, 2014). "In addition, autoimmune mice on the BXD2 background express elevated levels of IL-17A and spontaneously develop GCs before the formation of pathogenic autoantibodies, further supporting a role for IL-17A in B cell responses." (PMID 23505568, 2013). "Because IL-17A is a stimulator of pro-inflammatory cytokines, IFN-γ and IL-12, it could be the inducer of the Th1 response that has been reported previously to be linked to autoimmunity in autism." (PMID 22748016, 2012). "This suggests a potential mechanism where defective Treg function could lead to ongoing autoimmunity, characterized by the loss of FOXP3 expression under inflammatory conditions and induction of proinflammatory cytokines such as IL-17A and IFN-γ (IFN-γ+ FOXP3+ IL-17A+)." (PMID 38731877, 2024). "Rac1 forms a complex with Tiam1 and regulates the transcription of interleukin 17A (IL17A) and autoimmunity." (PMID 34079763, 2021). "Studies from models of autoimmunity indicate that regulatory CD4+ T cells and IL-10 represent a fundamental mechanism for regulating IL-17A." (PMID 34772416, 2021). "Even though the main source of IL-17A is the Th17 CD4+ αβ T cell population, in the onset of autoimmune pathologies, innate immune cells, especially those belonging to the γδ T cell subset, also contribute to the production of IL-17A." (PMID 30386339, 2018). "Given the active role of γδ T cells in the development of autoimmunity, it is possible to speculate that the mentioned immunotherapies could act not only on conventional Th17 T cells but also on γδ T lymphocytes because they express IL-23R and produce substantial quantities of IL-17A and IL-22." (PMID 30386339, 2018).